Y_RNA (Y RNA )
Gene: Miscellaneous RNA gene on chromosome 8 (113,950,886 to 113,950,998, forward strand). Ensembl gene ENSG00000206719.
Homologues: Orthologues: chimpanzee Y_RNA (98% identical), macaque Y_RNA (96% identical). Paralogues in human: RNY1 (88% identical), Y_RNA (88% identical), Y_RNA (87% identical), Y_RNA (86% identical), Y_RNA (85% identical), Y_RNA (84% identical), RNY1P11 (83% identical), Y_RNA (83% identical), RNY1P7 (82% identical), RNY1P8 (82% identical), Y_RNA (82% identical), Y_RNA (81% identical), and 97 more.